TAGLN (transgelin)
Diseases named in the same sentence as TAGLN in open-access papers (continued):
Sharing a sentence is not in itself a finding about the gene and the disease.
tumor (continued). "Interestingly, we found that TAGLN was mainly detected in fibroblasts derived from tumor stroma, rather than in tumor cells." (PMID 23510049, 2013). "Similarly, other investigators discovered that the TAGLN is not expressed in the malignant cells but in mesenchymal cells of the tumor stroma." (PMID 23510049, 2013). "Additionally, TAGLN is involved in the disintegration of the extracellular matrix (ECM) and angiogenesis during smooth muscle development, stem cell differentiation, and embryonic blood vessel formation, thereby contributing to tumor cell invasion and angiogenesis." (PMID 37365287, 2023). "Preliminary experiments did not yield differences in survival of tumor‐bearing mice and the lack of changes in HDAC2 and TAGLN expression among treatment groups as a pharmacodynamic study suggested that ineffective drug concentrations were achieved." (PMID 38087889, 2024). "The results showed that the expression of Transgelin in ESCC was not significantly correlated with the gender, degree of tumor differentiation, tumor location, and tumor diameter of patients (P > 0.05)." (PMID 34552870, 2021). "The results of this study further showed that the downregulation of Transgelin expression was not related to the location of ESCC, but was significantly related to the stage and grade of tumor." (PMID 34552870, 2021).
cancer (98 papers, 2007 to 2026). A tumor composed of atypical neoplastic, often pleomorphic cells that invade other tissues. "On the other hand, the additional 5 genes showed a high R-index = 0.9 or beyond, and COL11A1 and TAGLN expressions as shown in red letters were uniquely associated with SPARC expression in cancer stroma of the TNBC tumors (both R-index below 0.6 in total BC)." (PMID 39335478, 2024). "Transgelin/SM22 has been found in association with remodeling of the actin cytoskeleton and promotes the migration and invasion of cancer stem cells." (PMID 37363722, 2023). "Analysis of pan-cancer Genomic Profiles indicated that increased TAGLN was associated with poor survival in most epithelial cancers, especially OC." (PMID 34538264, 2021). "Overexpression of TAGLN was associated with cell invasion, which in turn contributed to promoting cancer metastasis." (PMID 32410620, 2020). "On the other hand, transgelin expression in cancer cells have reported to be down-regulated, and was associated with poor prognosis." (PMID 33297976, 2020). "Global gene expression profiling of TAGLN-overexpressing or TAGLN-deficient CRC cell lines revealed deregulation of multiple cancer-related genes and signaling pathways." (PMID 32393769, 2020). "Both up-regulation and down-regulation of transgelin has been linked to cancer development and progression." (PMID 28670517, 2017). "Furthermore, transgelin is associated with the remodeling of the actin cytoskeleton and promotes the migration and invasion of cancer stem cells." (PMID 32774160, 2020). "Transgelin, TGLN, is an actin-binding protein whose expression is upregulated by high cytoskeletal tension and is also known to play a role in cancer." (PMID 39960760, 2025). "Transgelin expression is up-regulated in several cancer types indicating possible role in oncogenesis and shown to promote the proliferation and differentiation of mesenchymal stem cells from bone marrow." (PMID 38708150, 2024). "Although TAGLN expression was dominantly observed in cancer stromal fibroblasts, a certain population of cancer cells also expressed TAGLN." (PMID 38514830, 2024). "They observed higher mRNA and protein expression levels of TAGLN in normal tissues compared to carcinoma cells." (PMID 39284282, 2024). "Recent studies highlighted the TAGLN functions in fibroblasts and their crosstalk with cancer cells." (PMID 36990991, 2023). "Calponin and transgelin have been found to closely related to cancer metastasis and autoimmune diseases." (PMID 37363722, 2023). "As an actin crosslinking protein, TAGLN participates in cell movement by improving the formation of podosomes and several biological processes related to cancer progression, such as differentiation, proliferation, migration/invasion, and apoptosis." (PMID 36990991, 2023). "TAGLN expression was lower in cancer samples compared to normal tissues, and CDC42 expression was negatively correlated with the prognosis of COAD patients." (PMID 37365287, 2023). "It is worth noting that TAGLN seems to participate in promoting and suppressing cancer in regulating the progression of malignant tumors." (PMID 36523769, 2022). "As an actin-monomer binding protein, TAGLN was even found to be overexpressed in different cancer entities, and correlated with advanced prognostic features." (PMID 35155239, 2022). "We analyzed the average correlation between Transgelin and functional status, including invasion, differentiation, metastasis, cell cycle, stemness, and proliferation, in different cancers through the CancerSEA database." (PMID 34552870, 2021).
cancer (continued). "Cluster 0 cells showed fibroblast signatures (RGS5 and NDUFA4L2), cluster 2 cells had strong expression of cancer associated fibroblast (CAF) markers (LUM, SFRP4, and COL1A1), and cluster 5 cells expressed myofibroblast markers (MYH11, TAGLN, and ACTA2)." (PMID 33662621, 2021). "In this study, the expression of Transgelin in cancer tissues, LGIN, HGIN, and normal esophageal mucosa tissues was further detected by immunohistochemistry." (PMID 34552870, 2021). "Abundant proteins localized mainly in the ECM, which are known EMT activators (e.g., collagen 1, fibulin 5), or promoters (transgelin) in different human cancers, were observed." (PMID 34572331, 2021). "The highest transgelin protein level was found in 786-0 cells derived from primary ccRCC carcinoma that were selected for functional characterization." (PMID 34572331, 2021). "Similar to TGFβ, TAGLN expression and function in cancer biology are dependent on the type and stage of cancer, hence the role of TAGLN in CRC biology is controversial." (PMID 32393769, 2020). "The results of several studies on the tumorigenic and non-tumorigenic cell lines indicated that the metastatic potential of cancer stem cells arises from highly expressed transgelin." (PMID 31391093, 2019). "We identified potential novel upstream regulators (e.g., CNOT7, SPDEF, MITF, and PAX5) controlling distinct clusters of genes within the HPV-host cell network as well as distinct factors (e.g., CPPED1, LCP1, and TAGLN) with essential functions in cancer." (PMID 30918060, 2019). "In the prostate study, TAGLN levels were found to be elevated in the stroma but decreased in the carcinomic epithelial cells during cancer progression." (PMID 31591355, 2019). "Results of RT-qPCR and immunoblot assays indicated that TAGLN expressions were higher in bladder smooth muscle cells, fibroblast cells, and normal epithelial cells than in carcinoma cells (RT-4, HT1376, TSGH-8301, and T24) in vitro." (PMID 31591355, 2019). "Our results indicated that the expression of transgelin, a regulator of the actin cytoskeleton, is higher in bladder normal epithelial cells than in carcinoma cells." (PMID 31591355, 2019). "As an abundant protein of smooth muscle cells and an important factor regulating the actin cytoskeleton dynamics, transgelin has been reported to be involved in many cancer-related processes." (PMID 29416680, 2018). "Recently, both FGF1 and TAGLN have been identified as highly correlated cancer biomarkers in a cross‐tissue analysis of gene expression in cancer tissues." (PMID 28510269, 2017). "Perhaps because of its abundance, transgelin has been frequently identified in proteomic profiling studies of cancer." (PMID 26847345, 2016). "Only the expression of the cancer-associated gene TAGLN,which encodes transgelin, was altered by FA in all three cell lines." (PMID 27293554, 2016). "We identified six genes including UNG, FUCA2, DERA, GMFB, TF, and SNX24 as significantly downregulated and two genes including MYL9 and TAGLN as significantly upregulated upon mir-145 over-expression in distinct cancer types." (PMID 27655328, 2016). "TAGLN expression was previously found to be downregulated in several types of cancer and transformed cells." (PMID 26421063, 2015). "Since DNA methylation alteration of the TAGLN gene was reported in cancers, we attempted to investigate the TAGLN gene methylation level in the primary NF1-deficient cells." (PMID 25109740, 2014). "Overexpression of the TAGLN protein has been observed in carcinomas of the stomach, liver, and oesophagus." (PMID 21304530, 2011). "These genes, including immunoglobulin-related genes, Transgelin (TAGLN), Keratin 19 (KRT19), Metastasis-associated lung adenocarcinoma transcript 1 (MALAT1), and superoxide dismutase (SOD2), play a role in the EMT process in various cancers." (PMID 41035074, 2025). "TAGLN rescue can inhibit the aggressive phenotype of let-7c-5pon in cancer cells." (PMID 39308508, 2024).
cancer (continued). "Calponin and transgelin play a major role in tumorigenesis and cancer metastasis." (PMID 37363722, 2023). "TAGLN is an actin-binding protein that may modulate the actin cytoskeleton, regulating cancer cell proliferation and migration." (PMID 37274283, 2023). "This function of transgelin/SM22 may be via suppression of metallomatrix protease-9 (MMP-9) that is upregulated in those types of cancer." (PMID 37363722, 2023). "For immune-related genes, the expression of genes involved in the categories of tight junction such as MYH11, PPP2R2C, and MYL9, cancer development such as TAGLN and CALD1, and acquired immunity such as PCP4 and CXCL13 was upregulated in the LP group when compared with that in the CON group." (PMID 37731924, 2023). "A decreased proliferation rate was also observed in other cell lines with silenced transgelin expression: in SW620, HT-29 and RKO colorectal, MDA MB 231 breast, BxPC3 and SW1990 pancreatic, and A549 and H358 lung cancer cell lines after silencing transgelin expression by RNAi." (PMID 34572331, 2021). "The role of TAGLN in different types of cancer is complicated." (PMID 34646394, 2021). "In addition, several investigations have shown that Transgelin in normal and cancer cells directly interact with the actin, and alter the motility of the cells." (PMID 31315664, 2019). "The depletion of TAGLN resulted in an increase in the capacity of cells to go initiate spontaneous podosome formation, with a concomitant increase in the ability of invasion from Matrigel assays; therefore, TAGLN seemed to be a marker of active stromal remodeling in vicinity of invasive carcinomas." (PMID 31591355, 2019). "Suppression of TAGLN expression has subsequently been reported in other cancers." (PMID 28248256, 2017). "The significance of these changes in gene expression will be taken up in the Discussion; all of the genes are related to the cytoskeleton or cancer, and concordant regulation by transgelin in two independent CRC lines suggests a general effect with a common mechanism." (PMID 26847345, 2016). "Thus the changes in TAGLN expression induced by FAtreatment would be consistent with promotion of a cancer phenotype in MCF10A and Hs578Tcells, but suppression of a cancer phenotype in MCF7 cells." (PMID 27293554, 2016). "However, proteomic studies of transgelin in human cancers often indicate up-regulation in aggressive, late-stage disease." (PMID 26847345, 2016). "It is possible that TAGLN acts differently in mesenchymal SMCs and in epithelial origin of cancer cells, as protein profiles might differ among different cell types, affecting the functions of individual proteins." (PMID 26421063, 2015). "The molecular mechanisms of transgelin in cancer development remain poorly understood." (PMID 25109740, 2014). "Similarly, transgelin (TAGL) has been shown to be associated with cell migration and invasion of cancer stem cells." (PMID 24283668, 2013). "Additionally, we found that TAGLN depletion inversely correlates with preoperative bilirubin levels (unconjugated; P ═ 0.003), which serves as an indicative marker of tumorigenicity in cancer cells." (PMID 39284282, 2024). "Thus, TAGLN promotes cancer stem cell survival in hypoxia and informs a novel therapeutic paradigm." (PMID 38087889, 2024). "Therefore, COMP and TAGLN are promising new targets for the treatment of malignant tumors." (PMID 32754278, 2020). "However, results from the functional assays of TAGLN in different cancers are still inconclusive." (PMID 31591355, 2019). "The myCAFs have been defined as α‐smooth muscle actin (αSMA)‐and transgelin (TAGLN)‐high expressing CAFs with a contractile phenotype, located in close contact with cancer cells." (PMID 39523476, 2025). "Cytoskeletal regulators (MYL9, TAGLN) and transcription factors (SNAI2) promote EMT and cancer stemness, while PMEPA1, IL6, IL8, IGFBP3, INHBA, and VEGFA contribute to proliferation, angiogenesis, and immune modulation." (PMID 41009714, 2025).
cancer (continued). "The RT-qPCR analysis indicated that mRNA expression of CAF markers (ACTA2, TAGLN, and LIF) was increased when fibroblasts were educated by cancer cells (gray bars, cancer-EV + CAF)." (PMID 39261905, 2024). "Significant differences were observed in the protein concentration levels of S100P, PIGR, C1QBP, TAGLN, and CNN1 between cancer and inflammatory lesions (P ═ 0.0006, P ═ 0.0032, P ═ 0.0008, P < 0.0001, P ═ 0.0094, respectively)." (PMID 39284282, 2024). "As expected, most up-regulated proteins are related to cancer genes, with seven of them known to be enhanced in PCa (SYNM, DES, MYH11, TAGLN, CNN1, LMOD1, and PGM5)." (PMID 38052461, 2024). "Significant differences were observed in protein concentration levels between cancer and inflammatory lesions for S100P, PIGR, C1QBP, TAGLN, and CNN1 (P ═ 0.0006, P ═ 0.0032, P ═ 0.0008, P < 0.0001, P ═ 0.0094, respectively) as shown in." (PMID 39284282, 2024). "Transgelin (TAGLN) is a mesenchymal protein involved in the EMT process and plays a regulatory role in a variety of cancers." (PMID 36523769, 2022). "Proteomic studies of human cancer are not in universal agreement with respect to the role of transgelin, and it will be important to identify the root cause of the discrepancies, which could relate either to different patient populations or to technical factors." (PMID 26847345, 2016). "At the same time, multiple collagen-related genes (COL6A2, COL3A1, COL4A1, and COL4A2) in the MSC-2 cluster were upregulated in bone metastases, which is consistent with our observation of IGFBP3, TAGLN, LUM, COL6A1, COL6A2, and COL3A1 in pan-cancer in Fig. (1d)." (PMID 39156727, 2024). "Calponin and transgelin exhibit similar expression in smooth muscle and non-smooth muscle cells, such as fibroblasts, lymphocytes, neural cells, and cancer cells." (PMID 37363722, 2023). "Multiple biologicalGO enrichments in the candidates could be dissected, for example,response to leptin and regulation of proteolysis increased in cancer(including STAT3 and transgelin (TAGL))." (PMID 35605973, 2022). "Transgelin (Tagln), an actin-binding protein, also promotes EMT in cancer cells, and expression changes of these genes could be indicative of cytoskeletal remodeling." (PMID 36149903, 2022). "For example, Calponin gene CNN1, TAGLN, and TMP2 are co-expressed in different cancers." (PMID 34261540, 2021). "In HPV-positive HNSC, the expression of TAGLN is significantly decreased, while AURKB is strongly upregulated, suggesting that HPV might be responsible for gene alterations that are important in cancer development in general." (PMID 30918060, 2019). "In addition, fibroblasts (n = 1 068) were identified by COL1A1 and FAP, endothelial cells (n = 2 561) were positive for RAMP2 and CLDN5 expression, smooth muscle cells (n = 1 100) were defined by TAGLN and CNN1, and epithelial/cancer cells (n = 319) were labeled by KRT14 and KRT17." (PMID 40360503, 2025). "Moreover, stromal TAGLN expression was higher in metastatic tissues than in nonmetastatic cancer tissues." (PMID 36990991, 2023). "Therefore, both transgelin and DIAPH3 shared similar biological function of actin-binding to assemble actin cytoskeleton and exhibited opposite clinicopathological relevance between cancer cells and fibroblasts." (PMID 33297976, 2020). "Transgelin is abundant in normal tissue and is not a marker of cancer per se." (PMID 26847345, 2016). "One hypothesis that fits with most of the experimental and clinical data is that transgelin is not a marker of cancer per se, but rather a marker of metastatic potential in advanced disease." (PMID 26847345, 2016).
cancer (continued). "TAGLN and TAGLN3 are homologues of TAGLN2, and TAGLN3 is a novel neuron-specific protein and has not been reported in cancer." (PMID 21304530, 2011).
infection (5 papers, 2010 to 2024). The state of being infected such as from the introduction of a foreign agent such as serum, vaccine, antigenic substance or organism. "Cofilin and transgelin were undetectable at 30 min after infection but were continuously up-regulated in the induced larvae after 22 hours." (PMID 20142993, 2010). "Briefly, it was shown that infection of endometrial cells led to the activation of transforming growth factor-β (TGF-β) signalling, causing quiescent fibroblasts to transform into transgelin (TAGLN)-positive myofibroblasts, giving the cells the ability to adhere and proliferate in vitro." (PMID 39595151, 2024). "The result showed that some mesenchymal markers, such as COL1A1, α-SAM, and TAGLN, faded and endothelial markers PROX1 and PDPN increased starting at the fourth day post-infection." (PMID 34936683, 2021).
adenocarcinoma (4 papers, 2012 to 2020). A common cancer characterized by the presence of malignant glandular cells. "R-Ras was mainly expressed in crypt epithelial cells, which are the main origin of CRC (e.g. adenocarcinoma, > 90% of CRC cases), while Transgelin was mainly expressed in the cells of the lamina propria." (PMID 27270312, 2016).
kidney disease (4 papers, 2013 to 2024). "Proteins linked to kidney diseases, including heat shock protein family B (small) member 1 (HSPB1), S100A6, transgelin (TAGLN), and TIMP metallopeptidase inhibitor 3 (TIMP3), were shown to be enriched in the proteome unique to AL." (PMID 38892061, 2024). "In a previous study, we identified the new podocyte cytoskeletal protein transgelin in a rat model of PAN‐induced kidney disease using high‐throughput microarray analysis." (PMID 32583562, 2020).
cardiovascular diseases (3 papers, 2017 to 2023). "PECAM (ECs) cell marke and TAGLN (SMC marker) have been used to assess reendothelialization rate of endothelial cells in several cardiovascular disease studies." (PMID 35370672, 2022).
prostate (2 papers, 2011 to 2012). "The loss of transgelin is a characteristic signature of colon and prostate carcinogenesis and its restoration suppresses colon tumorigenity in vivo and in vitro." (PMID 22506042, 2012).
metabolic disorders (1 paper, 2022). "Besides mutations and polymorphisms in TAGLN, epigenetic TAGLN modifications related to metabolic disorders could, therefore, also be linked to lipid levels." (PMID 34902367, 2022).